LBHD1 (LBH domain containing 1)
Synonyms: C11orf48; MGC2477
Tractability: No criterion of Open Targets' tractability assessment is met for any kind of drug.
Gene: Protein-coding gene on chromosome 11 (62,662,817 to 62,672,267, reverse strand). Ensembl gene ENSG00000162194.
Subcellular location (Human Protein Atlas): Nucleoplasm; Cytosol
Gene Ontology:
Biological process: positive regulation of DNA-templated transcription
Cellular component: nucleus
Genetic constraint (gnomAD): Loss-of-function variants: 26 observed, 28.16 expected, observed/expected ratio (o/e) 0.92, 90% interval 0.68 to 1.28. The upper end of that interval is the gene's LOEUF score, 1.28, which puts it in group 5 of 6, group 1 being the genes least tolerant of losing a copy. Missense variants: 335 observed, 324.14 expected, observed/expected ratio (o/e) 1.03, 90% interval 0.94 to 1.13. Synonymous variants: 104 observed, 118.89 expected, observed/expected ratio (o/e) 0.87, 90% interval 0.75 to 1.03.
Homologues: Orthologues: chimpanzee LBHD1 (98% identical), dog LBHD1 (72% identical), rabbit LBHD1 (68% identical). Paralogues in human: LBH (9% identical).
Diseases named in the same sentence as LBHD1 in open-access papers:
LBHD1 is named in the same sentence as 13 diseases in open-access papers, as found by Europe PMC text mining. Sharing a sentence is not in itself a finding about the gene and the disease. The quoted sentences say what the papers report.
bladder cancer (1 paper, 2019). "To address the potential functional relationship between LBHD1 and bladder cancer, we examined the LBHD1 expression at the mRNA and protein level in 5 different bladder cancer cell lines: J82, T24, 253J, 5637, and BLZ-211." (PMID 33817179, 2019). "LBHD1 was identified as a potential tumor antigen which is predominantly expressed in human bladder cancer tissue and localizes predominantly in the cytoplasm by immunohistochemical analysis in our previous research." (PMID 33817179, 2019). "Knocking down LBHD1 expression with LBHD1 siRNA significantly attenuated cell migration and invasion in cultured bladder cancer cells, and overexpressing LBHD1 with LBHD1 cDNA plasmids exacerbated cell migration and invasion." (PMID 33817179, 2019). "LBHD1 (C11ORF48) is one of the ten potential tumor antigens identified by immunoscreening the urinary bladder cancer cDNA library in our previous study." (PMID 33817179, 2019). "In order to explore the potential functional relationship between LBHD1 and bladder cancer, the expression of LBHD1 in 5 different bladder cancer cell lines at both the mRNA and protein level was analyzed." (PMID 33817179, 2019). "In the present study, we found that LBHD1 is differentially expressed in five different bladder cancer cell lines." (PMID 33817179, 2019). "By the construction of a urinary bladder cancer cDNA library, we found ten bladder cancer tumor antigens including LBHD1." (PMID 33817179, 2019). "The expression of LBHD1 at the mRNA and protein level was detected by RT-PCR and western blot in five bladder cancer cell lines." (PMID 33817179, 2019). "LBHD1 high and low expressing cells were used to investigate the migration, invasion, and proliferation of bladder cancer cells following transfection of LBHD1 with siRNA and plasmids, respectively." (PMID 33817179, 2019). "But the mechanism of LBHD1 involvement in bladder cancer is still unclear." (PMID 33817179, 2019). "Moreover, LBHD1 high and low expressing cells were used to study the migration, invasion, and proliferation of bladder cancer cells following transfection of the LBHD1 gene through siRNA or plasmids." (PMID 33817179, 2019). "Collectively, these findings suggest that LBHD1 may be a promising molecular marker for bladder cancer and provide a basis for further analysis of LBHD1 function in bladder cancer migration and invasion." (PMID 33817179, 2019). "Knockdown of LBHD1 with siRNA decreased 67-75% of cell migration and invasion in BLZ-211 bladder cancer cells These results suggested that LBHD1 might be involved in the migration and invasion of BLZ-211 cells and that LBHD1 siRNA negatively affected these behaviors." (PMID 33817179, 2019). "The role of LBHD1 in bladder cancer development has not been as well characterized." (PMID 33817179, 2019). "Whether LBHD1 is related to the occurrence and prognosis of bladder cancer has not been reported." (PMID 33817179, 2019).
cancer (1 paper, 2019). A tumor composed of atypical neoplastic, often pleomorphic cells that invade other tissues. "Similarly, LBHD1 was significantly overexpressed after the LBHD1 plasmid pc-LB was transfected into 253J cells, which promotes cancer cell migration and invasion." (PMID 33817179, 2019).
tumor (1 paper, 2019). "Moreover, the levels of LBHD1 expression in surgical specimens and their associations with tumor grade/stage as well as patient outcomes need further study." (PMID 33817179, 2019).
LBHD1 also shares sentences with these, for which no sentence is quoted: congenital heart disease (2 papers); nasopharyngeal carcinoma (2); rheumatoid arthritis (2); asthma (1); breast carcinoma (1); developmental delay (1); Epicanthus (1); infection (1); Intellectual disability (1); neuromuscular disease (1).